HNF1A (HNF1 homeobox A)
Diseases named in the same sentence as HNF1A in open-access papers (continued):
Sharing a sentence is not in itself a finding about the gene and the disease.
HNF1A also shares sentences with these, for which no sentence is quoted: maturity-onset diabetes of the young (31 papers); leptospirosis (5); dyslipidaemia (4); glioma (4); Crohn disease (2); glycogen storage diseases (2); Immunodeficiency (2); lung adenocarcinoma (2); neonatal diabetes mellitus (2); Nephropathy (2); non-small cell lung carcinoma (2); prostate adenocarcinoma (2); RCAD) syndrome (2); Wilson disease (2); acute liver failure (1); acute myeloid leukemia (1); adenocarcinoma (1); allergic asthma (1); Alzheimer disease (1); Aphasia (1); Arthritis (1); Ataxia (1); atrophic gastritis (1); B-Cell CLL (1); B-Cell Lymphoma (1); Beckwith-Wiedemann syndrome (1); blood platelet disease (1); calculus (1); carcinoids (1); clear cell carcinoma (1).
A further 66 diseases each share a sentence with HNF1A in 1 paper.